INS (insulin)
Diseases named in the same sentence as INS in open-access papers (continued):
Sharing a sentence is not in itself a finding about the gene and the disease.
diabetes (continued). "BMPs, a highly conserved subgroup of the TGF-β superfamily, critically regulate glucose homeostasis and insulin resistance in the setting of diabetes." (PMID 37240345, 2023). "Other agents used in diabetes, such as insulin secretagogues, including sulfonylureas and glinides, bind to sulfonylurea receptors on the pancreas beta cell and stimulate insulin release." (PMID 37185411, 2023). "Hypoglycemia, or low blood glucose, is a common complication of insulin treatment among people with type 1 diabetes mellitus (T1DM) and insulin-treated type 2 diabetes mellitus (T2DM)." (PMID 37773626, 2023). "The proportions of ketosis-prone diabetes and the body fat-related and insulin-resistant subgroup were similar between Ghana and Europe." (PMID 37402743, 2023). "Patients in the afternoon/night group had more comorbidities such as diabetes mellitus requiring insulin, hypertension, chronic heart failure, had more preoperative use of clopidogrel, and less use of aspirin." (PMID 36602973, 2023). "In diabetes, the incidence of uric acid stone formation is high due to insulin resistance, a decrease in urinary pH, and obesity which favors uric acid and mixed urate-calcium oxalate stone formation." (PMID 37007314, 2023). "Our prospective study revealed that preserved insulin secretory function and newly diagnosed diabetes at the time of kidney transplantation were favorable factors for which glucose metabolism did not worsen or improve 1 year after kidney transplantation." (PMID 37424863, 2023). "Diabetes mellitus (DM), a metabolic disorder that causes polyphagia, polydipsia, polyuria, and weight loss clinically, is characterized by an absolute or relative lack of insulin secretion and decreased sensitivity of target organs to insulin." (PMID 37089923, 2023). "This is an additional “trap” for the unwary and should be highlighted during the education provided by the diabetes team before initiation of insulin pump therapy." (PMID 37568965, 2023). "Diabetes, arises from either an absolute or relative insufficiency of insulin or insulin resistance of peripheral tissues." (PMID 38206747, 2023). "Rehabilitation services promoting physical activity are crucial for the management of diabetes as physical activity can improve hemoglobin A1c levels, insulin sensitivity, and glucose uptake." (PMID 37893825, 2023). "In the near future, the use of these computational tools should permit patients with T2DM to optimize their personal meal schedule and insulin dose, according to the severity of their diabetes." (PMID 37089422, 2023). "Sleep insufficiency can adversely affect carbohydrate metabolism and levels of endocrine hormones such as insulin, cortisol and leptin, which can lead to changes in appetite and glucose metabolism, accelerating the development of obesity and diabetes." (PMID 37082612, 2023). "The proportions of cardiometabolic risk factors, including diabetes, hypertension, family history of CAD, and the use of insulin and oral hypoglycemic drugs, were higher in the T3 group than in the other two groups (all P < 0.05)." (PMID 36864455, 2023). "Despite controlling several complications of diabetes by exogenous insulin, multiple complications of this disease are common in the cardiovascular system, kidney, retina, lens of the eye, peripheral nerves, and skin." (PMID 38113243, 2023). "Insulin and its analogs are the most common injectable diabetes drugs for patients with severe pancreatic dysfunction." (PMID 36904097, 2023). "The data showed a considerable rise in MDA and GSSG and a noteworthy decrease in GSH, all of which were insulin secretion hinders, leading to insulin-dependent diabetes mellitus." (PMID 37367922, 2023). "Women with insulin-treated diabetes were less likely to undergo axillary lymph node dissection relative to their non-diabetic counterparts." (PMID 37800138, 2023).
diabetes (continued). "While good or improved glycemic control (a low or lowered HbA1c level) is observed with intensive insulin treatment and/or diabetes technology management therapies, high rates of LGA or macrosomia and other complications can still persist." (PMID 36653533, 2023). "As there is insulin resistance in diabetes, the inability of insulin to suppress liver glucose production leads to hyperglycemia." (PMID 36839280, 2023). "Our study identified six cases with mothers who had diabetes requiring insulin therapy during pregnancy." (PMID 36999085, 2023). "Type-2 diabetes mellitus is brought about by a blend of insulin opposition and insulin emission disability." (PMID 37394484, 2023). "The availability of new treatments for diabetes based on immunomodulation and differentiation strategies is currently unsatisfactory as an alternative to exogenous insulin administration." (PMID 36829683, 2023). "Diabetes mellitus (DM) is a metabolic disorder characterized by chronic hyperglycemia related to deficits in insulin production." (PMID 36835159, 2023). "By contrast, chronically elevated glucose levels that occur during diabetes impair β cell insulin secretion and have been shown experimentally to suppress insulin translation." (PMID 38032734, 2023). "Recent evidence indicates that lncRNAs, through β-cell mass modulation, affect insulin synthesis, secretion and signaling, thereby enhancing the progression of type-2 diabetes mellitus (T2DM)." (PMID 37093889, 2023). "Diabetes is a metabolic derangement characterized by insulin insensitivity resulting from insulin resistance, reduced insulin production, and eventual pancreatic beta-cell failure, leading to hyperglycemia." (PMID 37955955, 2023). "The A24D variant is associated with inefficient cleavage of preproinsulin, whereas the V92L variant weakens the affinity of insulin for insulin receptor, and both lead to mutant INS gene–induced diabetes of youth." (PMID 36983642, 2023). "Subcutaneous short-acting insulin was started according to a sliding scale, in addition to long-acting basal insulin (the patient had brittle diabetes with fluctuations in his blood glucose readings, which was difficult to control." (PMID 37854477, 2023). "Cationized SF MNs are expected to replace subcutaneous injections of insulin as a new modality for diabetes treatment." (PMID 36810381, 2023). "In most situations, diet, oral hypoglycemic medications, or, in rare circumstances, insulin can be used to treat diabetes in glucagonoma syndrome." (PMID 37628857, 2023). "This study aimed to identify factors that improve appropriate manner in which individuals with diabetes who require insulin therapy dispose of medical sharps." (PMID 38099003, 2023). "Recently, sulforaphane were reported to protect cardiomyocytes from the attack of diabetes, reduce the accumulation of lipid peroxide, and alleviate insulin resistance via the essential AMPK/Nrf2/GPx4 axis." (PMID 36829795, 2023). "The currently recommended way of starting insulin therapy in people with T2D is the addition of basal insulin to the prior pharmacological treatment in conjunction with revisiting health behaviour and diabetes self-management education and support." (PMID 36882852, 2023). "The ultimate aim is to develop wearable, sensitive, stable and ideally non-invasive sensor platforms for the concurrent and continuous monitoring of insulin and glucose utilising artificial intelligence techniques to assist with the management of diabetes." (PMID 37504117, 2023). "Diabetes mellitus is a chronic disease of elevated blood glucose levels due to either suboptimal production of insulin by the pancreas or peripheral resistance of the body to insulin." (PMID 36604682, 2023). "A critical aspect of β cell function that is affected in diabetes is the ability to secrete insulin in response to elevated blood glucose levels." (PMID 38007492, 2023).
diabetes (continued). "This was a concern with our sample because only 31.2% of Hispanics with diabetes took insulin at least once." (PMID 36673730, 2023). "Clinically, the findings of the present study that suggest the possible involvement of PPARα ligands in insulin secretion provide new information for the treatment of diabetes as well." (PMID 37697384, 2023). "Diabetes mellitus is a metabolic disorder characterized by resistance to the action of insulin, insufficient insulin secretion or both." (PMID 37053209, 2023). "This includes requiring life-long hormone replacement, with rates of 10% for thyroid replacement (hypothyroidism), 1% for corticosteroid replacement (adrenal insufficiency) and 0.5–1% for insulin replacement (diabetes)." (PMID 37627153, 2023). "Type 1 diabetes mellitus (T1D) is an autoimmune disease reducing insulin production and therefore requires daily insulin administration." (PMID 37491278, 2023). "For women with type 2 diabetes, particularly those who were relatively newly diagnosed, it was difficult to navigate the new diagnosis along with the pregnancy and the addition of insulin to their diabetes management." (PMID 37131168, 2023). "The MTZ treatment of the transgenic zebrafish led to selective ablation of insulin-secreting pancreatic beta cells, resulting in hyperglycemia, followed by diabetes." (PMID 37237607, 2023). "Bacteroides were considered the effective degraders for polysaccharides, which play a positive role in diabetes by up-regulating glucagon-like peptide-1 and serum insulin levels." (PMID 37894615, 2023). "It was shown that a certain concentration of aqueous mulberry leaf extract repaired the islet cells of type 1 diabetes mellitus mice, promoting normal insulin secretion." (PMID 37504259, 2023). "These devices can collect extensive data on an individual's glucose patterns and insulin requirements, allowing for more personalized and precise diabetes management." (PMID 38239544, 2023). "Ferroptosis promotes the development of diabetes by participating in glucose-stimulated insulin secretion (GSIS) impairment and arsenic-induced pancreatic damage." (PMID 37667364, 2023). "The aim of the research question and purpose of the study was to investigate how adults with diabetes requiring insulin therapy perceive diabetes apps based on the 3 key psychological needs described by the SDT: competence, autonomy, and connectivity." (PMID 36826987, 2023). "This upregulation is believed to contribute to the pathogenesis of diabetes by affecting pancreatic beta-cell function and insulin secretion." (PMID 38139275, 2023). "Pioglitazone is an insulin resistance inhibitor widely used as monotherapy or combined with metformin or insulin in treating type 2 diabetes mellitus (T2DM)." (PMID 37095270, 2023). "Transfection of adipocytes with a miR146a inhibitor resulted in reduced insulin sensitivity and another study has shown that patients with diabetes mellitus have lower levels of miR146a in their peripheral blood mononuclear cells compared to controls." (PMID 37917636, 2023). "In 1921, Frederick Banting and Charles Best isolated insulin from pancreatic islets and administrated it to patients suffering from type 1 diabetes, thus inaugurating a new era in diabetes treatment." (PMID 37176684, 2023). "A significant number of patients with type 2 diabetes mellitus (T2DM) had poor glycemic control for extended periods of time before treatment intensification with oral antidiabetic drugs (OADs) or insulin was initiated." (PMID 36676805, 2023). "Our findings strongly indicated that canagliflozin treatment increases the risk of developing osteomyelitis from the very early stage of diabetes mellitus, before the advanced stage when insulin is prescribed." (PMID 36865915, 2023). "Complications associated with diabetes are life-threatening and the current standard of care for T1DM consists still of insulin injections." (PMID 36677212, 2023).
diabetes (continued). "Insulin secretion was severely impaired in the first principal gene-eigenvector, indicating that it corresponds to relatively late stage of diabetes." (PMID 37816033, 2023). "In this study, oral LPS administration suppressed the onset of type 2 diabetes mellitus in KK/Ay mice by increasing the expression levels of insulin signaling-related factors in adipose tissues." (PMID 36902049, 2023). "Type 2 diabetes mellitus is brought on by hyperglycemia from insulin resistance or inadequate insulin production from the pancreatic beta cells." (PMID 38074026, 2023). "An adequate selenium intake can act as an insulin‐mimetic to attenuate diabetes, with the role of reducing glucose and insulin tolerance, and therefore, preventing hepatic insulin resistance." (PMID 37324888, 2023). "Among the patients with comorbid diabetes, 82 (1.3%) received metformin 500 mg, 106 (1.7%) were prescribed Glimepiride 2 mg, and 88 (1.4%) were treated with insulin (specifically Apidra, Novorapid, and Levemir)." (PMID 37606390, 2023). "The other anti-diabetes drugs didn’t have such significant impacts on maintaining glucose stability, even the insulin or GLP-1 analog." (PMID 37098548, 2023). "Diabetes mellitus is a chronic metabolic disorder characterized by an excessive increase in glucose levels in the serum as a result of unbalanced insulin production and/or acuity to the hormone’s action on cellular receptor signaling." (PMID 36985818, 2023). "Beta cell function and insulin sensitivity were determined by modelling of OGTTs performed in 658 autoantibody-positive participants followed longitudinally in the Diabetes Prevention Trial–Type 1 (DPT-1)." (PMID 36459177, 2023). "For example, people who depend on specialized medications, like refrigerated insulin for diabetes, will likely face additional challenges in receiving treatment and care during extreme heat, floods, disasters, and other adverse events." (PMID 37662592, 2023). "Incidence of SCA was significantly higher in diabetes people using insulin compared to insulin-naïve diabetes people, which was consistent across all LDL-cholesterol level." (PMID 36803488, 2023). "Short-term treatment with insulin is recommended for patients with uncontrolled diabetes resulting in clinical symptoms and/or HbA1c greater than 9%." (PMID 38138975, 2023). "The second one is the most common type of diabetes, in which hyperglycemia is mainly due to insulin resistance and reduction of insulin production." (PMID 36062030, 2023). "PA improves glycemic control in patients with diabetes by enhancing insulin secretion and insulin sensitivity, and by stimulating glucose uptake by skeletal muscle and reducing body weight against a background of poor β-cell function." (PMID 37836486, 2023). "Diabetes mellitus (DM) is a common metabolic disorder resulting from insufficient insulin secretion or insulin action that leads to elevated blood glucose levels." (PMID 37082121, 2023). "Diabetes in older age is a very heterogonous illness related to various levels of decreased insulin sensitivity and insulin secretion defect." (PMID 38017369, 2023). "Pancreatogenic diabetes was characterized by a lower body mass index (BMI), required more insulin, had more episodes of hypoglycemia, but had lower rates of dyslipidemia and hypertension." (PMID 36979645, 2023). "The synthetic amylin mimetic pramlintide is an approved treatment for diabetes (both type 1 and 2) mostly in combination with insulin." (PMID 37049856, 2023). "In recent clinical trials in patients with NAFLD, improving insulin sensitization using diabetes treating agents (i.e., a GLP-1 agonist) was shown to improve liver histology in NAFLD." (PMID 37408268, 2023). "Gdf-3 has been identified as an important pathway for promoting insulin sensitivity in the S273A knockin lineage developed by homologous recombination in mESCs, which indicates a promising target for diabetes and obesity modulation." (PMID 37189379, 2023).
diabetes (continued). "Restrictions in access to diabetes care quickly lead to the deterioration of health, especially in patients requiring an intensification of insulin therapy, developing complications and with diabetic foot syndrome." (PMID 38201852, 2023). "Mg supplements increase insulin sensitivity and improve glycemic control in people with insulin resistance and diabetes." (PMID 36769401, 2023). "This has led to improved protocols for generating insulin-producing cells from pluripotent stem cells that can be transplanted into patients with diabetes." (PMID 37977142, 2023). "Whole body TXNIP-deficient and β-cell-specific TXNIP knockout mice have decreased β-cell apoptosis, increased β-cell mass, elevated insulin levels, and are protected from diabetes (for review see 153)." (PMID 37008937, 2023). "Additionally, inflammation in the metabolic and adipose tissues is associated with insulin intolerance in both obesity and diabetes, causing the pancreatic beta cells to start producing more insulin in order to keep blood sugar levels regular, which could result in circulating hyperinsulinemia." (PMID 37175908, 2023). "And for patients who have problems with eyesight, as a complication of [diabetes], it becomes a challenge for them to draw the accurate figures of insulin, the dosage." (PMID 37291520, 2023). "Diabetes can be classified as type 1 diabetes (insulin-dependent diabetes mellitus) and type 2 diabetes (non-insulin-dependent)." (PMID 37510181, 2023). "Small molecules that target kinase proteins have been shown to be successful in animal models of insulin resistance and diabetes, primarily by re-establishing insulin homeostasis." (PMID 37872245, 2023). "Diabetes mellitus/ hyperglycemia is a metabolic disease seriously effective from defects in insulin secretion and/or insulin action on receptor locus and is mostly considered by raised blood glucose levels." (PMID 37193696, 2023). "The PCP learned about tapering insulin and received feedback from the learning network on how to safely and effectively taper insulin use based on the needs of this person with diabetes." (PMID 37535407, 2023). "Through its impact on insulin secretion regulation both in vivo and in vitro, MT can impact metabolic diseases such as diabetes." (PMID 37655263, 2023). "At this time, gluconeogenesis is inhibited, resulting in lipid accumulation, and the adipose tissue of insulin-sensitive tissues reduces its insulin sensitivity, that is, insulin resistance, which in turn keeps blood sugar levels high, leading to diabetes." (PMID 37893758, 2023). "The most common type of diabetes requiring insulin therapy in children is type 1 diabetes mellitus, with monogenic forms of diabetes affecting just 1.1–4.2% of those with childhood diabetes." (PMID 36869270, 2023). "Fretful cholesterol, triglycerides, hypertension, sugar profiles and high incidence in females was evident in Type II (Non-Insulin Dependent) Diabetes Mellitus." (PMID 37471425, 2023). "T2DM constitutes up to 95% of all diabetes and is characterized by chronic hyperglycemia due to the disorders of insulin secretion and/or insulin action and impaired lipid and protein metabolism." (PMID 37786444, 2023). "Insulin-naive patients with diabetes mellitus chose their own insulin injector within a newly developed structured SDM process to meet the national guideline." (PMID 37005930, 2023). "Based on this evidence, current medical practice guidelines now strongly recommend RT-CGM for all persons with diabetes treated with intensive insulin therapy, defined as 3 or more doses of insulin per day or the use of an insulin pump." (PMID 36602920, 2023). "In contrast, peripheral vascular disease, insulin-treated diabetes, male gender, and type 2 diabetes diagnosis were identified as risk factors in the older group, increasing the risk of a positive non-hyperemic assessment by around 2–2.5 times." (PMID 37893581, 2023).